MDM4 (MDM4 regulator of p53)
Diseases named in the same sentence as MDM4 in open-access papers (continued):
Sharing a sentence is not in itself a finding about the gene and the disease.
glioma (29 papers, 2008 to 2024). A benign or malignant brain and spinal cord tumor that arises from glial cells (astrocytes, oligodendrocytes, ependymal cells). "Conversely, later-onset gliomas were associated with the IDHwt subtype paired with EGFR or MDM4 amplification, as well as with CDKN2A, CDKN2B, or PTEN deletion (FDR <0.015)." (PMID 34788626, 2021). "Here, we conducted a case-control study of the MDM4 gene to evaluate the potential associations between genetic variations and glioma risk in Han Chinese population." (PMID 30038284, 2018). "The aim of this study was to investigate whether common variants of MDM4 contribute to the risk of glioma in Han Chinese individuals." (PMID 30038284, 2018). "Recently, MDM4 gene has been reported to be a susceptibility gene for glioma in Europeans, but the molecular mechanism of glioma pathogenesis remains unknown." (PMID 30038284, 2018). "However, most studies focus on transcriptional levels, and little research has been designed to investigate the association between glioma and mutations of MDM4, which may be the root cause of the transcript variants of MDM4." (PMID 30038284, 2018). "Other studies found that the enhanced circ_0079586 can predict the poor prognosis of glioma and accelerate its progression through the interaction with miR-183-5p/MDM4." (PMID 34433131, 2021). "Since MDM4 was only amplified in neural stem cells, neural stem cell are likely to be at the origin of the glioma stem-like cells #10, #993 and G112." (PMID 28415661, 2017). "IDHwt GBM PDOXs retained common glioma mutations, including EGFR, MDM4, PTEN, PIK3CA, and PTCH1." (PMID 33009951, 2020). "Given the lack of rare variant data, these SNPs may not be sufficient to comprehensively evaluate glioma risk associated with the MDM4 gene." (PMID 30038284, 2018). "Histologically, the high-level expression of MDM4 correlates with worse differentiation in HNSC, Glioma (GBMLGG) and LIHC." (PMID 38281029, 2024). "Hence, MDM4 may be involved in the onset and development of glioma." (PMID 30038284, 2018). "In conclusion, gene amplifications specifically gene amplifications of DDB1, EGFR, MDM4 and GFAP can provide information about the cell types and the degree of heterogeneity at the origin of glioma stem-like cells." (PMID 28415661, 2017). "Variants in 1q32.1 (MDM4), 16q12.1 (HEATR3), 22q13.1 (SLC16A8) and 11q14.1 were also associated with increased risk of IDH-wt glioma although the results were not significant after adjusting for multiple comparison." (PMID 31842352, 2019). "More studies focusing on the pathological mechanisms of non-GBM glioma and MDM4 are still needed to unravel the role of MDM4 in the onset and development of non-GBM glioma." (PMID 30038284, 2018).
glioma (continued). "Therefore, based on our results, we hypothesize that the SNP rs4252707 may contribute to the risk of developing non-GBM glioma by somehow influencing the expression of MDM4, such as by affecting the splice sites or by being closely linked with some functional variations." (PMID 30038284, 2018). "Our results provide strong evidence that the MDM4 gene is tightly linked to genetic susceptibility for non-GBM risk in Han Chinese population, indicating a important role for MDM4 gene in the etiology of glioma." (PMID 30038284, 2018).
ovarian carcinoma (21 papers, 2010 to 2023). A malignant neoplasm originating from the surface ovarian epithelium. "Conversely, the MDM4-rs4245739*A allele has been linked to increased MDM4 expression and poorer outcomes in ovarian cancer." (PMID 37345045, 2023). "The A-allele of MDM4 rs4245739A>C (SNP34091) was associated with increased expression of MDM4 mRNA and protein levels by miR-191-5p regulation in ovarian carcinomas and sensitivity for chemotherapy." (PMID 27462918, 2017). "In order to estimate the potential impact of MDM4 SNP34091 status on ovarian cancer risk, we compared the frequency of the MDM4 SNP34091 genotypes among ovarian cancer patients (n = 1385) to healthy female controls (n = 1870)." (PMID 26867771, 2016). "In a study on 417 Caucasian patients with OC, another potential miR-409-3p recognition site polymorphism, MDM4 rs10900596 G > A, was related to an improved treatment response in ovarian cancer." (PMID 27834829, 2016). "Particularly, since in EOC, the metastatic potential is tightly linked to chemoresistance, we investigated whether MDM4 affects ovarian cancer progression by impairing metastatic properties." (PMID 34052831, 2021). "A recent study revealed that variant allele of MDM4 3’-UTR polymorphism rs4245739 abrogates the miR-191 target site and results in increased MDM4 expression, which was associated with increased risk for recurrence, accelerated tumor progression, and chemotherapy resistance in ovarian carcinoma." (PMID 27834829, 2016). "Taken together, these data demonstrate that high expression of MDM4 inhibits ovarian cancer cell spreading by affecting the early features of the EOC metastatic cells, migration, and invasion." (PMID 34052831, 2021). "The high number of ovarian cancer samples showing exclusive-nuclear staining compared to A2780 cells overexpressing MDM4 is probably due to the different levels of MDM4 in the two cell systems." (PMID 31547268, 2019). "To confirm the estrogen-dependent nuclear re-localization of MDM4, we performed co-immunofluorescence analysis of ERα and MDM4 in A2780 ovarian cancer cells." (PMID 31547268, 2019). "A SNP in the 3′UTR of MDM4 caused the acquisition of an illegitimate miR-191 target site, reducing MDM4 expression, and significantly delaying ovarian carcinoma progression and tumor-related death." (PMID 28831115, 2017). "The binding of miR-191 to MDM4-C allele mRNA, which could result in the increased expression of MDM4, may explain tumor progression in different types of cancers such as ovarian cancer and retinoblastoma." (PMID 36765828, 2023). "Although increased MDM4 levels have been associated with better prognosis and cisplatin chemosensitivity in ovarian cancer, subcellular localization of MDM4 has not been investigated in tissue specimens." (PMID 31547268, 2019). "Based on identification of selected loci in MDM4, studies have now demonstrated associations between MDM4 SNP loci with risk of breast and ovarian cancers as well as age of onset of ovarian cancers and hormone receptor negative breast cancers." (PMID 20111735, 2010). "To ascertain the function of MDM4 in EOC progression, we analyzed the dissemination of EOC cells by IP injection of the human ovarian cancer cell line SK-OV-3." (PMID 34052831, 2021).
lung cancer (20 papers, 2010 to 2025). A malignant neoplasm involving the lung. "In lung cancer cells, luteolin triggered death of cancerous cells and also stopped carcinogenesis by targeting MDM4 and increasing miR‐34a‐5p expression." (PMID 39830909, 2025). "Our findings are in line with a previous study demonstrating that activated KRAS proto-oncogene and insulin-like growth factor 1 signaling induce MDM4 expression at least partially via ELK1 in breast, colon, and lung cancer cells." (PMID 33429878, 2021). "Interestingly, the MDM4 inhibitor, SJ‐172550, and the MDM2 inhibitor, nutlin‐3, showed a synergistic effect with erlotinib in erlotinib‐resistant lung cancer cell lines, NCI‐H820 and NCI‐H1975." (PMID 33188726, 2021). "Three other drugs (SJ‐172550 for MDM4, nutlin‐3 for MDM2/MDM4, and carfilzomib for PSMA6 and PSMB6) showed improved IC50 values when used as a monotherapy but increased efficacy when used in combination with erlotinib on NCI‐H820 lung cancer cell lines." (PMID 33188726, 2021). "Studies have shown that in lung cancer, after aberrant splicing, the expression of BCL2L1, MDM2, MDM4, NUMB, and MET may play an important role in tumorigenesis, which may be due to the effects on cell apoptosis, cell proliferation, and intercellular cohesion‐related pathways." (PMID 33047900, 2020). "Moreover, miR-1205 could act as a tumor suppressor in nonsmall cell lung cancer by disconnecting the synergy between KRAS and MDM4/E2F116." (PMID 31801947, 2019).
prostate carcinoma (20 papers, 2011 to 2024). A carcinoma that arises from epithelial cells of the prostate gland. "The SNP34091C variant creates a functional target site for hsa-miR-191, and both ovarian and prostate cancer cells harboring the C- allele displayed reduced MDM4 mRNA and protein levels." (PMID 26867771, 2016). "Another SNP that has an association with aggressive prostate cancer is rs4245739 that is located in the 3′ untranslated region (UTR) of MDM4 on chromosome 1q32." (PMID 27070714, 2016). "Regarding prostate cancer risk, we observed a weak, non‐significant association between MDM4 SNP34091C and reduced risk in the dominant model." (PMID 26471763, 2015). "We uncovered that sustained depletion of MDM4 is growth inhibitory in prostate cancer cells, involving either apoptosis or senescence, depending on the cell and genetic context." (PMID 36010941, 2022). "Our novel findings uncovered MDM4 inhibition as a new concept for prostate cancer treatment, and we demonstrated efficacy and uncovered mechanisms of action." (PMID 36010941, 2022). "In this population‐based case–control study, we examined the potential association between MDM4 SNP34091, alone and in combination with the MDM2 SNP309T>G (rs2279744), and the risk of breast‐, colon‐, lung‐, and prostate cancer in Norway." (PMID 26471763, 2015). "We then used CRISPR–Cas9 to target MDM4 in multiple prostate cancer cell lines." (PMID 34552244, 2021).
prostate carcinoma (continued). "In order to assess the potential impact of MDM4 SNP34091 status on cancer risk, we compared the frequency of the MDM4 SNP34091 genotypes among breast‐ (n = 1,717), lung‐ (n = 1,331), colon‐ (n = 1,531), and prostate cancer (n = 2,500) patients to healthy controls (n = 3,747)." (PMID 26471763, 2015). "Compared with a negative control, proliferation of prostate cancer cells was significantly reduced (P < 0.0001; t-test) in response to MDM4 depletion using two distinct single-guide RNAs (sgRNAs)." (PMID 34552244, 2021).